REN (renin)
Diseases named in the same sentence as REN in open-access papers (continued):
Sharing a sentence is not in itself a finding about the gene and the disease.
prostate carcinoma (continued). "Similarly, MR analysis based on the Prostate Cancer Association Group to Investigate Cancer-Associated Alterations and the FinnGen cohort provided genetic evidence that the use of agents acting on the renin-angiotensin system decreased the odds of prostate cancer." (PMID 38487860, 2024). "Other studies have also suggested that blockade of the renin–angiotensin system by ACEIs and ARBs might have a protective effect against a broad range of cancer types, including lung, breast, and prostate cancers, by affecting cell proliferation, angiogenesis, and apoptosis." (PMID 33794209, 2021).
sarcopenia (13 papers, 2014 to 2025). Progressive decline in muscle mass due to aging which results in decreased functional capacity of muscles. "The normalization of elevated plasma renin activity reduced the loss of body fat and lean mass (cachexia/sarcopenia), p < 0.001) and prolonged survival (p < 0.05)." (PMID 31404946, 2019). "The normalization of plasma renin activity was associated with improved heart systolic function, reduced edema, diminished cachexia/sarcopenia, and prolonged survival." (PMID 31404946, 2019). "The possible mechanism by which RHF increases the risk of developing sarcopenia may be due to increased right atrial pressure and decreased stroke volume, leading to activation of the renin–angiotensin–aldosterone system and systemic venous congestion." (PMID 41440545, 2025). "Further studies will be necessary to determine the generalizability of these findings to other HF conditions associated with elevated renin activity and to further explore the mechanisms through which the normalization of plasma renin activity modulates fluid-retention/edema and cachexia/sarcopenia." (PMID 31404946, 2019). "We examined the pathophysiologic contribution of elevated plasma renin activity concentrations to the progression of HFrEF as assessed by the development of edema, cachexia/sarcopenia, and mortality, in a randomized and blinded study." (PMID 31404946, 2019). "The normalization of plasma renin activity attenuated cachexia and sarcopenia, independently of alteration of plasma Ang II levels, suggests that renin activity contributes directly or indirectly to this process." (PMID 31404946, 2019). "In a translational model of DCM with rEF, the normalization of elevated plasma renin activity concentration retards the progression of experimental HF by reducing the development of systemic edema, cachexia/sarcopenia, and mortality." (PMID 31404946, 2019). "In summary, the normalization of plasma renin activity retards the progression of experimental HF by improving cardiac systolic function, reducing the development of systemic edema, cachexia/sarcopenia, and mortality." (PMID 31404946, 2019). "Additionally, the overactivation of the renin-angiotensin system in skeletal muscle increases proteolysis and impairs muscle regeneration, perpetuating sarcopenia and dinapenia." (PMID 41439932, 2025). "The link between sarcopenia and renal hyperfiltration may be based on the interplay of various factors, including oxidative stress, insulin resistance and overactivation of the renin–angiotensin–aldosterone system." (PMID 38594601, 2024). "During aging, oxidative stress, intramyocellular lipid accumulation, the modified activity of insulin sensitivity regulatory enzymes, decreased autophagy, sarcopenia, mitochondrial dysfunction, and an over-activated renin-angiotensin system may occur." (PMID 36987444, 2023). "Our study may provide mechanistic insights into the beneficial effects of pharmacological inhibition of renin-angiotensin system in the prevention of age-related sarcopenia." (PMID 26571361, 2015).
cerebrovascular disease (12 papers, 2018 to 2025). "It is an important member of the renin-angiotensin system, which plays an important pathological role in cardiovascular and cerebrovascular diseases." (PMID 36344782, 2023). "As a biomarker of cardiovascular and cerebrovascular diseases, BNP is a peptide hormone mainly secreted by the heart, which possesses the functions of natriuretic, diuretic, vasodilator, hypotension, antagonizing renin-angiotensin-aldosterone, and inhibiting sympathetic excitation." (PMID 35928924, 2022).
focal segmental glomerulosclerosis (12 papers, 2007 to 2026). A renal disorder characterized by sclerotic lesions in the glomeruli. "Patients carrying APOL1 risk alleles (G1 and G2) have a higher risk of developing Focal Segmental Glomerulosclerosis (FSGS); we hypothesized that escalated levels of miR193a contribute to kidney injury by activating renin–angiotensin system (RAS) in the APOL1 milieus." (PMID 39766282, 2024).
ischemic stroke (12 papers, 2009 to 2023). A stroke disorder caused by obstruction of blood flow to the brain, due to thrombotic (local blood clot formation) or embolic (due to a blood clot or other material traveling from another site) event. "And elevated blood pressure was prevalent in the acute period of ischemic stroke, activating the renin–angiotensin–aldosterone system and in turn causing the production of angiotensin‐2, vasoconstriction, and erythropoietin." (PMID 33943024, 2021). "Exposure to cold ambient temperatures may lead to activation of the sympathetic nervous system and the renin‐angiotensin system and an increase in blood pressure, which may lead to plaque rupture and thus an increased risk of ischemic stroke." (PMID 37269140, 2023). "As a stressor, ischemic stroke led to increased activation of the sympathetic nervous system and the renin-angiotensin-aldosterone system, including increased serum catecholamine and angiotensin II (Ang II) levels in patients with ischemic stroke." (PMID 36778208, 2023). "Angiotensin II (Ang II), as the main bioactive peptide of the brain renin-angiotensin system, plays an essential part in the pathophysiology of ischemic stroke." (PMID 36388196, 2022). "ACE is involved in the Renin-Angiotensin-Aldosterone system and implicated in microvascular complications in Diabetes III (MVCD3) and ischemic strokes." (PMID 28553317, 2017). "Neuronal overexpression of brain ACE-2 is also neuroprotective in a chronic hypertension mouse model (transgenic for renin and angiotensinogen that overproduces Ang II) following experimental induction of ischaemic stroke." (PMID 27884212, 2016). "A number of interconnected pathways previously associated with ischemic stroke were over-represented in females, including TLR (Toll-like receptor), HMGB1, TREM1, PPARα/RXRα, Hypoxia, Renin-Angiotensin, Mitochondrial Dysfunction, Glucocorticoid receptor and cytokine signaling pathways." (PMID 25036109, 2014). "Therefore, the potential efficacy of acupuncture in ischemic stroke may be its influence on the endothelial nitric oxide system and brain renin-angiotensin system, which can enhance cerebral perfusion by affecting cerebrovascular reactivity." (PMID 36388196, 2022). "In summary, central application of Aliskiren, a clinically approved renin inhibitor, is neuroprotective and improves functional outcome in a model of ischemic stroke independent of its blood pressure lowering activity." (PMID 31551909, 2019). "Here, we report that central application of the renin antagonist Aliskiren, a clinically used antihypertensive drug, protects the brain after experimental ischemic stroke independent of its blood pressure lowering activity." (PMID 31551909, 2019).
mineralocorticoid excess (12 papers, 2010 to 2025). "The main reason behind this alkalemia seems to be mineralocorticoid excess caused by overactive renin-angiotensin system (RAS) activation." (PMID 36644034, 2022). "As levels of renin and aldosterone are classically low in this state, this condition has been termed the syndrome of apparent mineralocorticoid excess (SAME)." (PMID 40672027, 2025). "Suppression of plasma renin and aldosterone supported the diagnosis of apparent mineralocorticoid excess secondary to excessive liquorice consumption." (PMID 34362360, 2021). "Our family presented with features of mineralocorticoid excess, nephrocalcinosis, autosomal recessive inheritance pattern and varying degrees of renal dysfunction with low aldosterone and plasma renin activity (PRA)." (PMID 29067160, 2016). "Following the discontinuation of the interfering medication (an aldosterone receptor antagonist), biochemical analysis demonstrated normal plasma renin and aldosterone levels, thereby ruling out the hypothesis of mineralocorticoid excess." (PMID 39816312, 2024).
Addison’s disease (11 papers, 2005 to 2025). "Biochemical tests confirmed Addison’s disease, with normal electrolytes, normal renin and raised ACTH." (PMID 40980397, 2025). "Findings of high serum adrenocorticotropic hormone (ACTH) and renin, as well as low cortisol and aldosterone levels, helped establish a diagnosis of Addison's disease." (PMID 33747659, 2021). "Her initial renin level came back elevated at 14.727 μg/h/L (14.727 ng/mL/h) and she was positive for adrenal 21-hydroxylase antibodies, providing further evidence for Addison’s disease." (PMID 38744309, 2024). "A limitation to this case report is that we did not obtain cortisol or aldosterone levels; however, based on our patient’s clinical presentation, elevated ACTH and renin levels, and 21-hydroxylase antibodies, she was diagnosed with Addison’s disease and responded well to treatment." (PMID 38744309, 2024). "Despite having a low EF, our patient did not present with edemas, possibly due to the impaired renin-angiotensin-aldosterone system caused by Addison’s disease." (PMID 30458836, 2018). "Measurement of the plasma renin activity and aldosterone concentrations is also helpful: in Addison disease plasma renin activity is high (because of the low intravascular volume) and plasma aldosterone is low (because of inability of the adrenal cortex to produce it)." (PMID 16120008, 2005). "There is no consensus on the validity of plasma renin measurement for adjusting mineralocorticoid (MC) substitution in patients with primary adrenal insufficiency (PAI)." (PMID 39416427, 2024).
aortic stenosis (11 papers, 2016 to 2025). Aortic valve stenosis is a aortic valve disease caused by the incomplete opening of the aortic valve. "A retrospective analysis of patients with aortic stenosis showed that the course of calcification of the aortic valve was slowed by medication that inhibits the renin-angiotensin-aldosterone system." (PMID 40870420, 2025). "In the setting of the patient already treated with TAVR, there are studies suggesting a benefit of renin–angiotensin system inhibition in these patients undergoing TAVR for aortic stenosis, or at least in a notable proportion of them." (PMID 36937938, 2023).
Cushing syndrome (11 papers, 2010 to 2025). Cushing's syndrome (CS) encompasses a group of hormonal disorders caused by prolonged and high exposure levels to glucocorticoids that can be of either endogenous (adrenal cortex production) or exogenous (iatrogenic) origin. "However, the plasma renin activity surrogate calculated from RAS fingerprint analysis was about 40% lower in the group of patients with Cushing’s syndrome compared to the control group, which is comparable to previous publications reporting renin concentrations below or within the normal range." (PMID 39804209, 2025). "The two affected brothers of the propositus (subjects II.5 and II.7) had no clinical features of Cushing's syndrome despite hypercortisolism and insufficiently suppressed plasma or salivary cortisol with low or undetectable renin and aldosterone values." (PMID 21042587, 2010).
glomerulonephritis (11 papers, 2012 to 2024). A renal disorder characterized by damage in the glomeruli. "We aimed to evaluate the physiological response of a kidney damaged by glomerulonephritis to sodium load in an inhibited renin-angiotensin system." (PMID 39044930, 2024). "Recent evidence indicates that medications for the blockade of the renin-angiotensin system (RAS) pathway to reduce proteinuria in glomerulonephritis modulate erythropoiesis by regulation of angiotensin II signaling." (PMID 30700016, 2019). "Further diseases linked to PPROM were nephritis or glomerulonephritis (ACE, COL4A3, COL4A4, IGF1, NOS2, REN, TNF)." (PMID 25264875, 2014). "It is clear that Renin-Angiotensin System inhibitor and steroid treatment are effective in the majority of primary IgAN, but antibiotic therapy is still the first choice for glomerulonephritis related to staphylococcal infection." (PMID 27082609, 2016). "In our previous study including biopsy-proven glomerulonephritis patients, patients with high urinary AGT and renin showed significantly decreased proteinuria and increased eGFR during RAS-inhibitor treatment." (PMID 32410703, 2020).
hypovitaminosis D (11 papers, 2014 to 2024). "Interestingly, it has been previously reported that hypovitaminosis D is associated with increased blood pressure while vitamin D reduces RAS activity through specific suppression of renin secretion." (PMID 31284538, 2019). "Hypovitaminosis D is associated with greater plasma renin activity, inflammation, and higher blood pressure, and FGF-23 may play such roles in similar indirect ways, both of which are called phosphate-responsive hormones." (PMID 25033287, 2014). "Both hypovitaminosis D and SARS-CoV-2 elevate renin levels, the rate-limiting step in the renin-angiotensin-aldosterone system (RAS); it increases ACE-1 but reduces ACE-2 expression." (PMID 39452140, 2024).
injury (11 papers, 2014 to 2025). Damage inflicted on the body as the direct or indirect result of an external force, with or without disruption of structural continuity. "In recent years, the renin–angiotensin system (RAS) has been proposed as a target pathway for therapeutic interventions after brain injury." (PMID 35355989, 2022). "The objective of this study was to compare the protective effect of APX-115 with a renin-angiotensin system inhibitor (losartan), the standard treatment against kidney injury in diabetic patients, on streptozotocin (STZ)-induced diabetic kidney injury." (PMID 29088780, 2017). "Anti-inflammatory agents including PPAR-α agonists, PPAR-γ agonists, AT1 receptor antagonists, and renin-angiotensin system blockers have been under preclinical investigation as protectants against radiation-induced brain injury in mouse models." (PMID 27671196, 2016). "The postulated pathophysiology of CSW in head injury is (a) increased sympathetic activity and dopamine release causing natriuresis; (b) increased brain natriuretic peptide (BNP) by the injured brain; and (c) failure of renin aldosterone system." (PMID 27213068, 2016). "ACE2 is a master regulator of the renin-angiotensin system and has shown to be protective during SARS-CoV-2 infection by downregulating Ang II-mediated vascular permeability and acute lung injury." (PMID 35251001, 2022). "Vitamin D regulates the renin–angiotensin–aldosterone system (RAAS), decreasing renin and ACE expression and promoting ACE-2 expression, which may explain the possible protective role against acute lung injury." (PMID 35409648, 2022).
staphylococcus aureus infection (11 papers, 2019 to 2025). An infectious process in which the bacteria Staphylococcus aureus is present. "In Cluster 3, the upregulated genes were notably enriched in pathways such as viral protein interaction with cytokine and cytokine receptors, tyrosine metabolism, Staphylococcus aureus infection, and renin secretion." (PMID 41031266, 2025). "KEGG analysis of stage I endometrial carcinomas vs. atrophic endometrium revealed staphylococcus aureus infection, estrogen signaling pathway, IL-17 signaling pathway, Renin secretion, inflammatory response, JAK/STAT3, K-Ras, and TNFα/NF-κB." (PMID 37958433, 2023). "Upregulated expressed genes were mainly enriched into Wnt/-catenin signaling pathway, Thyroid hormone synthesis, Staphylococcus aureus infection, Retinol metabolism, and the Renin-angiotensin system." (PMID 34020675, 2021).
autosomal dominant tubulointerstitial kidney disease (10 papers, 2017 to 2024). "Autosomal dominant tubulointerstitial kidney disease due to REN mutation can be present in childhood." (PMID 37450011, 2024). "Heterozygous variants in the calcium-sensing receptor gene CASR (pLI = 0.05) can cause hypocalciuric hypercalcemia while autosomal-dominant tubulointerstitial kidney disease can be caused by variants in UMOD (pLI = 0), MUC1 (pLI = 0.02) or REN (pLI = 0)." (PMID 39099563, 2024). "To date, mutations in UMOD, HNF1B, REN and MUC1 have been shown to cause autosomal dominant tubulointerstitial kidney disease (ADTKD)." (PMID 28267784, 2017). "It shares some common features with autosomal dominant tubulointerstitial kidney diseases caused by mutations in MUC1 (mucin 1, 1q21), HNF1B (HNF1beta, 17q12), REN (renin, 1q32) and SEC61A1 (Sec 61 translocon alpha 1 subunit, 3q21)." (PMID 28437467, 2017). "Heterozygous mutations in the genes encoding uromodulin (UMOD), hepatocyte nuclear factor 1β (HNF1B), renin (REN) and mucin-1 (MUC1) can result in autosomal dominant tubulointerstitial kidney disease (ADTKD)." (PMID 28701203, 2017).
colorectal cancer (10 papers, 2014 to 2025). A primary or metastatic malignant neoplasm that affects the colon or rectum. "The SUCNR1 functions as a receptor for the citric acid cycle intermediate succinate, involved in the renin-angiotensin system and from its function less likely to be associated with a colorectal cancer risk." (PMID 26872740, 2016). "Clinical and experimental studies have shown that inhibitors of the classical renin–angiotensin system (RAS) reduce tumor progression and are associated with better outcomes in patients with colorectal cancer." (PMID 32448803, 2020).
cyst (10 papers, 2016 to 2025). A sac-like closed membranous structure that may be empty or contain fluid or amorphous material. "On the other hand, some studies have shown the prevalence of SRC is related to the increased renin release which due to renal ischemia caused by cyst expansion." (PMID 38172931, 2024). "ADPKD progression is associated with several pathways such as apoptosis, fibrosis, inflammation, cyst proliferation, renin–angiotensin system (RAS) activation, and kidney vasculature impairment." (PMID 28535817, 2017). "ADPKD cyst-derived cells in culture revealed that the renin is expressed primarily in cysts of distal tubule origin and in cyst-derived cells with distal tubule characteristics." (PMID 26753721, 2016). "Indeed, cyst pressure induces renin–angiotensin–aldosterone system (RAAS) activation and kidney hypoxia." (PMID 35327948, 2022). "One is renin synthesis by the cyst epithelium and dilated tubules." (PMID 30909873, 2019). "In addition, radiolabelling of renin and mRNA for renin has been detected in cyst wall epithelia and cyst fluids." (PMID 26753721, 2016). "Impaired polycystin 1 and 2 function leads to decreased nitric oxide release and synthesis, which then leads to renin–angiotensin–aldosterone (RAAS) activation and cyst growth." (PMID 37217845, 2023). "While in the general CKD population the negative effects of sodium intake are probably mediated via increased blood pressure and activation of the renin-angiotensin system, in ADPKD sodium-induced increase of vasopressin is a likely additional mechanism leading to cyst growth." (PMID 33677691, 2022).